TG (thyroglobulin)
Diseases named in the same sentence as TG in open-access papers (continued):
Sharing a sentence is not in itself a finding about the gene and the disease.
tumor (continued). "As was done in our case, some authors recommend thyroidectomy and 131I ablation as the first-line of treatment in order to be able to use the measurement of thyroglobulin as a tumor marker." (PMID 27882257, 2016). "The second case was diagnosed with the same method as in the specimen; the tumor was negatively stained by keratin, S100, and thyroglobulin, and positively stained by vimentin, desmin, and smooth muscle actin." (PMID 27080750, 2016). "Patients with incidental PTMC that underwent TT for BTD are easier to follow up, since we can then use thyroglobulin and thyroglobulin antibodies as tumour markers." (PMID 25925164, 2015). "Considering the low level of the specific tumor marker, thyroglobulin, a bone biopsy and resection of the shoulder mass were indicated." (PMID 26245479, 2015). "It facilitates radioactive iodine if required, allows optimal follow up using thyroglobulin as a tumor marker, and addresses concerns about multifocal disease within the gland." (PMID 26918146, 2015). "The histologic appearance of the tumor was suggestive of metastatic thyroid carcinoma, which we were able to confirm using IHC for thyroglobulin and TTF-1." (PMID 26550511, 2015). "Hürthle cell carcinomas are oxyphilic type of tumours, with histological features and ability of thyroglobulin production, which suggests that they arise from the follicular cells of the thyroid gland." (PMID 25810698, 2015). "Following initial therapy, the tumor marker thyroglobulin can be used during follow up to detect recurrence." (PMID 26918146, 2015). "In the differential diagnosis, tumor cells stained positive for thyroglobulin with immunohistochemical staining especially considering the areas of clear cell tumor." (PMID 24884725, 2014). "Although it was not statistically significant, methylation(+) cancer tended to show larger size of tumor (P = 0.06, t-test) and higher levels of thyroglobulin (P = 0.08, t-test)." (PMID 24367375, 2013). "Awareness about this phenomenon of tumor-to-tumor metastasis, careful examination of morphology and proper immunohistochemical staining such as Thyroglobulin and Napsin A are important for correct diagnosis and appropriate therapy." (PMID 23414265, 2013). "The tumor cells, with rounded nuclei, distinct nucleoli, and clumped chromatin, stained positive for thyroglobulin." (PMID 23336429, 2013). "Patients with positive PET lesions were significantly older (P = 0.03), had higher median serum thyroglobulin levels at the time of evaluation (32.9 versus 3.1 μl/L) (P = 0.024) and had a higher tumor, node, metastasis (TNM) stage (P = 0.01)." (PMID 22985118, 2012). "Thyroglobulin (TG) and thyroid peroxidase (TPO) expression was found to be significantly decreased in tumors, and the lowest level of TPO expression occurred in a tumor harboring both the p.A67GTTF-2 variant and a RET/PTC3 rearrangement." (PMID 22481925, 2012). "At 6 months after RAI therapy, 6 patients had progressive disease (defined as an increase >10% in serum thyroglobulin levels and/or an increase >25% in tumor dimensions); 2, stable disease." (PMID 23326755, 2012). "In patients with thyroglobulin > 10 ng/mL, therapy response was classified as partial remission, if imaging by CT and/or ultrasound showed shrinkage of the tumor, intensity of radioiodine uptake decreased and/or thyroglobulin levels were lowered." (PMID 24710197, 2011). "In patients in stable partial remission, an increase of the specific tumor marker thyroglobulin will indicate progression and the necessity to proceed with further courses of radioiodine therapy." (PMID 24710197, 2011). "The immunohistochemical studies for calcitonin along with thyroglobulin negativity usually confirm the C-cell origin of tumor cells." (PMID 22185367, 2011). "In the remaining 8% of the patients, partial remissions were observed (decrease of tumor volume, of intensity of radioiodine uptake and/or of thyroglobulin serum level)." (PMID 24710197, 2011).
tumor (continued). "Today, serum thyroglobulin (Tg) and high-resolution ultrasound (US) are the modalities used for tumor surveillance." (PMID 21969828, 2011). "That is, patients who have clinically detectable disease recur at a greater rate than those whose first recurrence is detected by thyroglobulin measurement or imaging modalities, stressing the need for early detection before tumor burden becomes significant." (PMID 19841680, 2009). "In 3 cases, immunostaining of the aspirated tumor cells with thyroglobulin antibody was performed, and in 1 case an aspiration smear was stained with commercial HMB-45 antibody." (PMID 17263878, 2007). "The tumor cells in this patient stained negatively with thyroglobulin antibody and further confirmed that the patient's lesion was a metastatic RCC." (PMID 17263878, 2007). "The tumor cell cytoplasm reacted negatively with thyroglobulin and positively with HMB-45 antibodies." (PMID 17263878, 2007). "Immunocytochemical staining of the aspirated tumor cells with thyroglobulin is useful for tumor typing as cells derived from a thyroid follicular tumor commonly express thyroglobulin." (PMID 17263878, 2007). "An elevated serum thyroglobulin level (> 800 ng/ml) supported the thyroid origin of the primary tumor." (PMID 16984659, 2006). "Mixed tumors have a common cell of origin; tumor cells show expression of both thyroglobulin and calcitonin." (PMID 16984659, 2006). "Colloid-like structures stained with anti-thyroglobulin (Tg) antibodies were observed in the tumours." (PMID 9000596, 1997). "Group 2 showed significantly higher rates of follicular carcinoma, tumor size > 2 cm, angiolymphatic invasion, pN1 disease, multicentricity, elevated postoperative thyroglobulin (Tg > 10 ng/mL), iodine-refractory disease, distant metastases, and higher late Tg levels (all p < 0.05)." (PMID 41819745, 2026). "Additionally, total thyroidectomy is recommended in MSO, not only to rule out primary thyroid carcinoma but also to facilitate RAI therapy and enable thyroglobulin to serve as a reliable tumor marker for surveillance." (PMID 40922876, 2025). "Considering thyroglobulin’s role as a tumor marker, absDPC may serve as an effective and practical DCL in the clinical setting." (PMID 39974195, 2025). "Aside from its association with FAP, the distinction of CMTC from PTC is clinically relevant as the lack of unequivocal follicular cell differentiation questions the potential benefits of serum thyroglobulin measurements for tumor surveillance and RAI-related adjuvant therapies." (PMID 40111709, 2025). "Additionally, it is crucial to treat MMFTC tumors as aggressive variants and monitor patients closely with neck ultrasounds and tumor markers (calcitonin, thyroglobulin, CEA) to detect early signs of recurrence and improve survival." (PMID 39295705, 2024). "Common diagnostic techniques of TC include histopathological evaluation of the thyroid gland tissue, fine needle aspiration cytology (FNAC), ultrasonography, and various laboratory examinations with the likelihood of estimating the tumour markers calcitonin and thyroglobulin." (PMID 39558949, 2024). "For patients without the BRAF mutation, age and advanced tumor stage similarly predict an increased risk of mortality, along with elevated levels of thyroglobulin and calcitonin." (PMID 39767732, 2024). "Similarly, thyroglobulin (TG) and BRAF V600E mutations were evaluated across subtypes to identify patterns correlating with tumor progression and prognosis." (PMID 39767732, 2024). "Additionally, this study examined the changes in tumor size and tumor-related marker Thyroglobulin (Tg) values in patients at 2, 6, and 12 months after the operation." (PMID 38988713, 2024). "In addition, I had the following questions: Was it due to assay variations, due to decrease in production of calcitonin and thyroglobulin, or due to decrease in tumor volume?" (PMID 36153411, 2023).
tumor (continued). "This phenomenon is well described in the literature, and hypotheses such as the greater antigenicity of tumor thyroglobulin may justify this finding." (PMID 37364146, 2023). "Serum thyroglobulin can be used as a detection index for tumor recurrence after operation." (PMID 36607876, 2023). "It was discovered that clinical characteristics including age, gender, tumor size, extrathyroidal invasion, multifocality, serum thyroglobulin (Tg), serum thyroglobulin antibodies (TgAb), radiomic and ultrasound characteristics might predict CLNM in PTC." (PMID 36875475, 2023). "Detectable thyroglobulin levels after the first treatment may indicate the presence of still viable tumor cells." (PMID 37627224, 2023). "Thyroglobulin was found to be a reliable tumor marker in both papillary and follicular tumors." (PMID 35154933, 2022). "The neoplastic cells were vaguely to markedly positive for thyroglobulin in all tumours." (PMID 34464021, 2022). "Thus, the decision to undergo surgery with FN/SFN considers other findings, such as the tumor size, the serum thyroglobulin level, ultrasound findings, tumor expansion into the mediastinum, autonomous functioning, and surrounding tissue compression." (PMID 35224273, 2022). "Thyroglobulin has been applied as a tumor marker in follicular tumors." (PMID 35154933, 2022). "Thyroglobulin (Tg) can be used as a tumor marker in patients who have undergone total thyroidectomy for thyroid cancer; however, in patients with thyroid, the American Thyroid Association does not support the use of serum Tg to screen for or detect thyroid cancer." (PMID 34631064, 2021). "Nanoparticles (NP) (mainly mesoporous silica, gold, carbon, or liposomes) have been developed to improve the detection of biomarkers and routine laboratory parameters (e.g., thyroid stimulating hormone, thyroglobulin, and calcitonin), tumor imaging, and drug delivery in TC." (PMID 34439219, 2021). "The current tumour marker, serum thyroglobulin that has a half-life of 65 h, may take at least 7–10 half-lives (4 weeks) for complete thyroglobulin clearance in the absence of metastases." (PMID 34512731, 2021). "The measurement of thyroglobulin and ultrasound of the neck are long established procedures to assess whether thyroid and/or tumor tissue is still present postoperatively, in the sense of a risk assessment." (PMID 39355644, 2021). "In multivariate analysis, four variables including high serum thyroglobulin antibody (TgAb) level (>1,150 IU/ml), lower tumor location, irregular margin of CLN, and micro-calcification in the CLN were determined to be significantly associated with the CLN metastasis in PTC patients with HT." (PMID 34367075, 2021). "Interestingly, the second patient did have a partial response of lung and liver metastases on imaging, and a transient decrease of the tumor marker thyroglobulin from 17 to 9 μg/L." (PMID 34120192, 2021). "Immunohistochemical staining revealed the tumor cells to be positive for thyroglobulin and TTF-1." (PMID 32390944, 2020). "In contrast, the tumor cells tested negative for p63, p40, smooth muscle actin, S-100, cytokeratin 5/6, thyroglobulin, BRAF V600E, and Epstein-Barr virus-encoded small RNAs." (PMID 32438756, 2020). "In such cases, preoperative thyroglobulin could better inform clinical decision making, providing information on the true tumor extent." (PMID 32182688, 2020). "We therefore hypothesized that preoperative serum thyroglobulin levels may also be related to tumor burden (primary tumor size, number of LNM) and extent of LNM (including distant metastasis)." (PMID 32182688, 2020). "We analyzed the correlations between the values of SUV and the presence of the BRAF mutation as well with other prognostic factors such as stage, age, specific tumor markers (thyroglobulin and anti-thyroglobulin), extrathyroid extension, the presence of metastatic lymph nodes or distant metastasis." (PMID 32575591, 2020).
tumor (continued). "By immunohistochemistry, the tumor cells are positive for thyroglobulin and TTF1." (PMID 32632840, 2020). "After adjusting for other factors (i.e., age, sex, tumor histology, and resection margins), there was also statistical significance between tumor burden and serum thyroglobulin levels (β ± SE = 0.10 ± 0.01, p < 0.001 for tumor size and β ± SE = 0.36 ± 0.02, p < 0.001 for number of LNM)." (PMID 32182688, 2020). "Recently, RAI therapy is widely used for adjuvant treatment after total thyroidectomy for the purpose of ablating unresectable residual lesions and meanwhile predicting tumor persistence or recurrence by monitoring the thyroglobulin (Tg) level and/or implementing of RAI whole-body scan." (PMID 31523497, 2019). "Hence, the aim of the work was to build a semi-mechanistic mathematical model that describes the tumor growth under RAI treatment using the thyroglobulin levels (Tg)." (PMID 28389624, 2017). "Moreover, the tumor cells lack immunoreactivity for the thyroid-specific markers TG, TTF-1, and TPO." (PMID 27082575, 2016). "Thyroglobulin is a specific tumor marker for follow-up of patients with DTC which have undergone total thyroidectomy with or without postoperative 131-iodine ablation, and the sensitivity of a Tg assay is important for a correct interpretation of clinical significance of minimal changes in serum Tg." (PMID 26695140, 2016). "The majority of these tumour cells expressed cytokeratins, thyroglobulin and NIS." (PMID 26178530, 2016). "Immunohistochemistry (IHC) of TTF-1 and thyroglobulin (TG) were positive in tumor cells." (PMID 26245479, 2015). "Thus, in the present case, the serum CA19-9 level was useful for monitoring recurrence and progression of the metastatic lesions, being a more effective tumor marker than the serum thyroglobulin level." (PMID 24407283, 2014). "Serum thyroglobulin and pro-gastrin-releasing peptide were elevated (93.2ng/mL and 75.2pg/mL, respectively), whereas other tumor markers, including carcinoembryonic antigen (CEA), carbohydrate antigen 19–9 (CA19-9), sialyl Lewis X and neuron-specific enolase, were all negative." (PMID 25532447, 2014). "Taking into account her history of thyroid pathology and the absence of a salivary mass, a rereading of the biopsy slides with immunohistochemical studies showed expression of thyroglobulin (Tg) by the tumor cells and confirmed zygomatic bone metastasis of a PTC." (PMID 22953123, 2012). "After thyroidectomy, thyroglobulin can be used as a tumor marker for follow-up." (PMID 21892277, 2008). "CD44 variations could serve as more reliable biomarkers for advanced or chemo-resistant TC compared to conventional markers like thyroglobulin, as they reflect the tumor’s ability to evade apoptosis, maintain stem-like features, and efflux drugs, factors central to MDR." (PMID 40363706, 2025). "But a low–intermediate-risk tumor with a low post-surgical thyroglobulin level may not necessitate RAI for either ablative or adjuvant purposes." (PMID 39272954, 2024). "The long-term persistence of thyroglobulin antibodies in tamoxifen-treated mice, however, potentially suggests a true association of these antibodies with PTC development, resulting from the appearance of novel, tumor-related epitopes within the large thyroglobulin molecule." (PMID 36077831, 2022). "This may be due to the deposition of thyroglobulin and clustering of the tumor cells in the LNs." (PMID 36038830, 2022). "Furthermore, two meta-analyses including one hundred and eighty-nine patients and two hundred and seventy patients with a local recurrence of their thyroid cancer found a significant decrease in volume and largest diameter of the tumor as well as thyroglobulin level before and after RFA treatment." (PMID 34248853, 2021).
tumor (continued). "A tumor related event is defined by the occurrence of subsequent treatment (RAI administration or surgery) for abnormal RAI uptake on the post-therapeutic whole-body-scan (WBS) or by elevated thyroglobulin (Tg) or Tg-antibody levels and/or abnormal neck ultrasound during controls." (PMID 39355644, 2021). "We evaluated whether preoperative serum thyroglobulin levels can predict tumor burden and extent." (PMID 32182688, 2020). "Moreover the tumour cells stain positively with thyroglobulin." (PMID 16984659, 2006). "Employing a novel algorithm capable of super‐resolution analysis of tumour ecosystems,15we first identified tumour cells based on the expression of EPCAM, TG, KRT18 and KRT19." (PMID 39810624, 2025). "Follow-up care should be adapted according to the tumor type: for PTC, thyroglobulin monitoring and whole-body scintigraphy are advised post-thyroidectomy, while CT imaging is essential for SCC." (PMID 40347268, 2025). "After two cycles of [177Lu]Lu-DOTA-TATE therapy, tumor growth was halted (TTV decreased from 385 mL to 273 mL) and the thyroglobulin tumor marker level decreased from 606 ng/ml to 273 ng/mL." (PMID 39404789, 2025). "Response was assessed by tumor control as defined by stable (± 30.0%) or decreasing (≥ 30.0%) total tumor volume (PET-derived TTV), thyroglobulin (Tg) and RECIST 1.1 criteria." (PMID 41023438, 2025). "Immunohistochemistry revealed that the tumor cells were positivefor cytokeratin AE1/AE3, hepatocyte nuclear factor-1-beta and PAX8 andnegative for thyroglobulin and thyroid transcription factor-1." (PMID 39700333, 2024). "Demographic data, tumor size, capsular/vascular invasion, extrathyroidal extension, local or distant metastasis, initial dose and cumulative dose of RAI, serum thyroglobulin(Tg), antithyroglobulin antibody(TgAb), and imaging findings were investigated." (PMID 39004697, 2024). "Immunohistochemistry revealed that the tumor cells were positive forcytokeratin AE1/AE3, hepatocyte nuclear factor-1-beta (HNF1β) and PAX8 andnegative for thyroglobulin and thyroid transcription factor-1 (TTF-1)." (PMID 39700333, 2024). "Thyroglobulin, thyroid transcription factor-1 (TTF-1), and other thyroid markers are commonly expressed by the tumor cells." (PMID 38947607, 2024). "Thyroglobulin levels in MTC, while lower than in PTC or FTC, also increase progressively with the advancing tumor stage (r = 0.68; p < 0.001)." (PMID 39767732, 2024). "Clinical characteristics, including age, sex, longest tumour diameter, lesion site, central and lateral LNM, and TT3, TT4, fT3, fT4, TSH, TG-Ab, TPO-Ab, and Tg levels, were compared among the three groups." (PMID 37884592, 2023). "Immunohistochemistry (IHC) revealed that the tumor cells in this lesion were positive for TTF-1, thyroglobulin, CK19, HBME-1, Galectin-3 and BRAF (V600E)." (PMID 37544981, 2023). "In the multivariate logistic regression analysis, longest tumour diameter, lesion site, LNM extent, and thyroglobulin concentration were significant mETE predictors." (PMID 37884592, 2023). "The tumor showed the expression of cytokeratins, such as CK8-18 and AE1/AE3, and typical CD99 expression, whereas immunostaining for thyroglobulin, TTF1, PAX8, calcitonin, CK20, SOX10, ERG, SMA, and NUT was negative." (PMID 36129618, 2022). "We tested metabolic tumor volume (MTV), total lesion glycolysis (TLG) on 18F-FDG-PET, and the progression of stimulated thyroglobulin within 4–6 months of initial radioiodine therapy as prognostic markers for OS." (PMID 33917322, 2021). "Thyroglobulin (Tg) is an important and easily measured tumor marker for DTC, which reflects the patient’s tumor burden and is influenced by the levels of thyroglobulin antibody (TgAb) and thyroid stimulating hormone (TSH)." (PMID 34040584, 2021).